ENSG00000273904
Gene: Gene (Ensembl biotype ribozyme) on chromosome 10 (114,168,156 to 114,168,280, reverse strand). Ensembl gene ENSG00000273904.
Gene Ontology:
Molecular function: catalytic activity